IL18 (interleukin 18)
Diseases named in the same sentence as IL18 in open-access papers (continued):
Sharing a sentence is not in itself a finding about the gene and the disease.
Sepsis (continued). "In sepsis, bacterial infection induces the excessive release of inflammatory cytokines, such as tumor necrosis factor (TNF)-α, interleukin (IL)-1, and IL-18, causing cellular injury and multiple-organ dysfunction syndrome." (PMID 38584827, 2024). "HLA-DR on HLA-DR+ NK cells can increase the level of IL-18, aggravating the mortality of sepsis patients." (PMID 39076981, 2024). "Elevated levels of IL-18 have been identified in patients with severe sepsis and are correlated with poor clinical outcomes, making IL-18 a potential therapeutic target for mitigating pyroptosis-induced damage." (PMID 39594987, 2024). "To this end, we administered recombinant IL-18 (rIL-18) to the KO mice immediately after sepsis and determined the degree of inflammation." (PMID 38720893, 2024). "In our study, we observed in mice that CLP-induced sepsis resulted in decreased survival, increased release of the pro-inflammatory cytokines IL-1β, IL-18, and TNF-α, and cardiac dysfunction." (PMID 38584827, 2024). "The results showed that the mRNA levels of NLRP3 and IL‐18 were significantly increased in sepsis patients compared with healthy controls." (PMID 39692606, 2024). "Consistent with our findings, IL-18 has been shown to play detrimental roles in septic conditions, including pneumonia-induced sepsis." (PMID 38720893, 2024). "Interleukin-18 (IL-18), a cytokine involved in the pyroptotic pathway, has been identified as a major driver of chronic inflammation and immune suppression in sepsis survivors." (PMID 39594987, 2024). "Correspondingly, quercetin significantly reduced serum levels of IL-1β and IL-18 in the mice with acute lethal sepsis." (PMID 39769989, 2024). "Strikingly, we find that the pairwise effects of tumor necrosis factor plus interleukin (IL)-18, interferon-gamma or IL-1β suffice to mirror the impact of sepsis across tissues." (PMID 38191855, 2024). "Similar to previous studies, our ICU-sepsis group displayed significantly increased interleukin (IL)-18, IL-1β, IL-6, CXCL-8, IL-10 and MCP-1 compared to either or both of the ICU-non-sepsis patient and healthy cohorts." (PMID 38410714, 2024). "Taking into consideration the fact that ‘sepsis is associated with the dysregulation of the immunological system’, the study aimed to check whether predictive models could benefit from possessing the information on the values of serum concentrations of sCD163 and IL-18." (PMID 36767629, 2023). "We have previously shown that simultaneous neutralisation of IL-1 and IL-18 is lifesaving in experimental sepsis models." (PMID 37582864, 2023). "There was a trend in the median values between the three groups in the concentrations of IL-18 and sCD163: the lowest values were observed in the control group, the intermediate values in sepsis, and the highest values in septic shock." (PMID 36767629, 2023). "Pro-inflammatory cytokines that are believed to be involved in excessive inflammation in sepsis are TNFα (tumor necrosis factor-alpha), IL-1β (interleukin-1β), IL-12 (interleukin-12), and IL-18 (interleukin-18)." (PMID 37627293, 2023). "Treatment with curcumin led to the regulation of protein expression of IKKβ, IκBα, p-NF-κB, TNF-α, IL-1β, and IL-18 stimulated by sepsis." (PMID 36756300, 2023). "The differences in the IL-18 concentration between sepsis and septic shock and in the sCD163 concentration between the control group and sepsis were insignificant (p = 0.3340; p = 0.2522, respectively)." (PMID 36767629, 2023). "In a sepsis model, astrocyte pyroptosis increased the release of pro-inflammatory cytokines (IL-1β and IL-18), resulting in neuron damage." (PMID 37353794, 2023). "The authors linked the increase in IL-18 and CD163 concentrations to two sepsis-associated phases: early pro-inflammatory and late, anti-inflammatory, respectively." (PMID 36767629, 2023). "The progression of sepsis is significantly influenced by the involvement of crucial cytokines such as IL-1β, IL-18, IL-6, IL-12, IL-17, and others." (PMID 38035100, 2023).
Sepsis (continued). "Broad-spectrum caspase inhibitors Z-VAD-FMK and VX-166 can reduce IL-1β and IL-18 release and show significant therapeutic effects against sepsis in human patients and rodent models." (PMID 36756123, 2023). "A comprehensive analysis was conducted to investigate the impact of senescence-related genes on sepsis, and 8 hub genes (IGFBP7, GMFG, IL10, IL18, ETS2, HGF, CD55, MMP9) associated with senescence were identified." (PMID 38259686, 2023). "Mature caspase-1 cleavages IL-1β and IL-18 into maturity, both of which play critical roles in the early phase of sepsis, with elevated levels exacerbating the inflammatory response." (PMID 37711629, 2023). "In this study, both sepsis and septic shock were characterized by a markedly elevated concentration of IL-18 compared to the control group." (PMID 36767629, 2023). "We found that Daph obviously protected animals from mortality, reduced the LPS-induced alveolar edema and inflammation cells infiltration in sepsis mice, and suppressed the production of pro-inflammatory factors including IL-1β, IL-18, IL-6, TNF-α and iNOS." (PMID 36998049, 2023). "In summary, our work demonstrates that P2X7 expression is highly induced in lymphocytes during sepsis, and this correlates with IL-18, along with other inflammatory mediators such as IL-6, IL-8, and procalcitonin." (PMID 38094297, 2023). "Upon admission, two subgroups (sepsis and septic shock) were characterized by markedly increased concentrations of IL-18 and sCD163." (PMID 36767629, 2023). "It is known that the activity of IL-18 is balanced by the presence of IL-18BPa, and serum IL-18BPa levels have been significantly elevated in sepsis and other inflammatory diseases." (PMID 36902104, 2023). "Double blockade of IL-1 and IL-18 was previously reported effective to reduce severity and mortality in a mouse sepsis model." (PMID 36964620, 2023). "While pyroptosis is the inflammatory form of RCD, it can release IL-1β and IL-18 in the early stages to initiate the event of sepsis." (PMID 36741074, 2023). "In this study, we identified 8 senescence-related genes (IGFBP7, GMFG, IL10, IL18, ETS2, HGF, CD55, and MMP9) and developed a diagnostic model for the prediction of sepsis occurrence." (PMID 38259686, 2023). "During the course of LPS sepsis (0–36 hpi), most PICCs reached the first and second peak at 6 and 16 hpi, respectively, with IL-6, IL-18, CCL5, CCL7 and CXCL1 sustaining at plateau at 36 hpi." (PMID 37332010, 2023). "Meanwhile, pneumonia-induced sepsis patients exhibited activation of NLRP3 inflammasome and production of the pyroptosis-associated pro-inflammatory cytokines IL-1β and IL-18." (PMID 36923408, 2023). "We showed that sepsis-exo or miR-885-5p mimic not only elevated IL-1β and IL-18, but also increased NLRP3, caspase-1, and GSDMD-N, leading to promotion of pyroptosis." (PMID 35345489, 2022). "Monitoring the level of IL-18 can effectively evaluate the severity and rehabilitation of patients with sepsis." (PMID 36199375, 2022). "In our study, the variance of IL-18 values in sepsis patients was much lower (range from 6 pg/ml to about 2000 pg/ml) than what was observed for IL-6 (from 6 pg/ml to almost 1 million pg/ml)." (PMID 36189302, 2022). "As the interferon-γ-inducing factor and a central inflammatory mediator, IL-18 has been demonstrated to play important roles in septic shock, organ failure, and sepsis mortality, suggesting a potential therapeutic target in sepsis." (PMID 35203474, 2022). "The higher the serum IL-18 level, the more severe the liver and kidney function and pathological injury, which is considered as a potential biomarker for sepsis patients." (PMID 36032662, 2022). "Our study highlighted two potential therapeutic targets in sepsis, i.e., the significantly increased LIGHT levels and the highly variable IL-18 levels across a subset of patients with sepsis." (PMID 35203474, 2022).
Sepsis (continued). "When we limited the analysis to those patients admitted to wards, circulating levels of all cytokines decreased from day 1 to day 5, with the only exception of IL-1β in septic shock patients and IL-18 in sepsis patients." (PMID 36189302, 2022). "Compared to plasma LIGHT levels, the increase in plasma IL-18 levels showed only nominal significance in patients with sepsis." (PMID 35203474, 2022). "Total IL-18 and IL-18BP are typically elevated in sepsis-induced HBD + DIC, albeit to a lesser extent than in MAS, but the increase in both suggests IL-18 has bioactive effects." (PMID 35190900, 2022). "Hyperferritinemia is also related to a pro-inflammatory state in sepsis, with increases of interleukin (IL)-6, IL-18, Interferon γ, sCD163 and a decrease of the IL-10/tumor necrosis factor α ratio as quantitative markers of inflammation." (PMID 36614993, 2022). "A previous study suggested IL-18 as a potential therapeutic target due to its crucial roles in sepsis." (PMID 35203474, 2022). "Treatment with anti-IL-18 neutralizing antibodies has been shown to have significantly protective effects in a mouse model of sepsis." (PMID 35203474, 2022). "Sepsis-exos also enhanced the secretion of IL-1β and IL-18 and decreased HMBOX1 expression in mRNA and protein levels." (PMID 35345489, 2022). "Sepsis-exos time-dependently elevated IL-1β and IL-18, increased miR-885-5p but decreased HMBOX1 expression." (PMID 35345489, 2022). "The positive correlation of HDL-POVPC levels with IL-18 endorsed the prognostic value of HDL-POVPC for sepsis." (PMID 35592322, 2022). "This study highlights the significant roles of LIGHT and IL-18 in the severity of sepsis, and, for the first time, we demonstrate a key damaging role of LIGHT in patients with sepsis complicated by ARDS or multi-organ failure." (PMID 35203474, 2022). "It is assumed that neutrophil pyroptosis in sepsis controls the level of IL-1β and IL-18 and therefore the excessive inflammation." (PMID 36068299, 2022). "The pathogen-associated molecular patterns and damage-associated molecular patterns in sepsis activate NLRP3 and caspase-1 to release inflammatory cytokines such as IL-18 and IL-1β, aggravating the inflammatory response." (PMID 36032662, 2022). "The observed significant variance in IL-18 levels between individuals with sepsis highlights its potential as a precision therapeutic target with neutralizing mAbs, by selecting patients with significantly elevated IL-18." (PMID 35203474, 2022). "Faisal reported that urinary IL-18 biomarkers at 6 h after sepsis had a sensitivity of 77.78%, specificity 82.60%, while at 48 h after sepsis had a sensitivity of 70.37% and specificity of 69.56% in detecting AKI." (PMID 36545669, 2022). "In our study, IL-18 levels were consistently observed for correlations with increased sepsis severity and sepsis complications in both bacterial and viral sepsis." (PMID 35203474, 2022). "Sepsis patients showed an increase in a few of the pro-inflammatory cytokines i.e., IL-6, IL-8, IL-18, IL-33, IP-10, MIF, MIP1a, MIP1β, and MIP3a, along with the growth factors i.e., LEPTIN, GCSF, MCSF and ESelectin." (PMID 35681439, 2022). "The expression of key inflammasome proteins NLRP3 and caspase-1 and pyroptosis-related proteins GSDMD, IL-1β, and IL-18 was decreased, suggesting that inhibition of pyroptosis also alleviated lung injury in mice with sepsis." (PMID 35188436, 2022). "The IL-18 levels are increased in many endogenous inflammatory processes, such as sepsis, and numerous studies have indicated IL-18 as both a mediator and a biomarker of AKI." (PMID 35054831, 2022). "TNF-α can induce the expression of IL-6, IL-10, and IL-18, which can be used as an inflammatory marker for the development of sepsis." (PMID 35698642, 2022). "This is consistent with previous findings that the increase of plasma IL-18 level has been shown as a biomarker for adverse outcomes of sepsis." (PMID 35592322, 2022).
Sepsis (continued). "We showed that sepsis-exo treatment elevated IL-1β and IL-18, decreased HMBOX1, and promoted pyroptosis in AC16 cells." (PMID 35345489, 2022). "Treatment of sepsis-exos significantly increased the serum levels of IL-1β and IL-18 72 h after surgery." (PMID 35345489, 2022). "We found an obviously higher transcriptional levels of IL-1β and IL-18 in macrophages in Card9−/−-sepsis mice." (PMID 35618701, 2022). "Both IL-1β and IL-18 are involved in sepsis, sepsis-induced muscle failure and sepsis-induced cardiomyopathy." (PMID 35615361, 2022). "Bacteremia and subsequent endotoxemia directly stimulate the release of inflammatory cytokines, including TNF-α, IL-1β, IL-6, IL-12, and IL-18 in sepsis." (PMID 36120368, 2022). "In sepsis models, there is substantial evidence that neutrophils undergo pyroptosis and that interleukin 18 (IL-18) and interleukin 1 β (IL-1β) levels are elevated." (PMID 36713461, 2022). "An increased serum IL-18 level indicates the severity of sepsis and is correlated with worse prognosis." (PMID 34257519, 2021). "The expression of IL-1β, IL-6, and IL-18 in lung tissues of sepsis-induced ALI mouse model was obviously decreased by the infection of lv-LBH (P < 0.001)." (PMID 33553423, 2021). "IL-18 has been shown to be an effective indicator for monitoring treatment efficacy and patient recovery in patients with sepsis." (PMID 35054259, 2021). "NLRC4 (NLR family CARD domain containing 4) was found to be up-regulated by MAPK pathway in pediatric sepsis, which also inhibited IL‐1β and IL‐18 production to contribute to the anti-inflammatory response." (PMID 33949285, 2021). "Serum ACLY level is an additional diagnostic and prognostic biomarker in pediatric patients with sepsis.The relationship between serum ACLY and IL‐18 and underlying mechanisms involved in pathophysiology of sepsis need further study in the future." (PMID 33378581, 2021). "IL-18 is regarded as an important factor in the pathophysiology of sepsis with IL-18 levels found to be increased in septic patients in several studies." (PMID 35054259, 2021). "It has been established that IL-18 is involved in the pathogenesis of inflammation, tumours, hemophagocytic syndrome, sepsis, AKI, various autoimmune diseases and cardiac ischemia." (PMID 35223418, 2021). "Many biomarkers such as procalcitonin (PCT) or interleukin (IL)-6 or IL-18 are used in clinical practice to facilitate the diagnosis of sepsis." (PMID 34577843, 2021). "Pellino1−/− mice suppressed the protein expression of Pellino1, TRAF6 and NF-κB and inhibited the levels of TNF-α, IL-6, IL-1β and IL-18 in mice of sepsis." (PMID 33632252, 2021). "Specifically, IL-18, a pleiotropic pro-inflammatory cytokine with abnormal expression in sepsis and a marker of inflammasome activity, has a documented value as a prognostic indicator for the outcome of critically ill septic patients." (PMID 35054259, 2021). "In vivo, overexpression of LBH decreased the lung histological changes, lung injury score, lung W/D ratio, expression of IL-1β, IL-6, and IL-18, and activation of NLRP3inflammasome in lung tissues of sepsis-induced ALI mouse model." (PMID 33553423, 2021). "We provide the first evidence of IL18/1IL-18BP implication in failed SBT in 30 min in patients recovering from sepsis." (PMID 35054259, 2021). "In a mouse model of Pseudomonas aeruginosa-induced sepsis, Atg7 gene knockout mice showed enhanced activity of inflammasomes in macrophages, accompanied by elevated blood levels of IL-1β and IL-18 and increased pyroptosis in macrophages." (PMID 34257519, 2021). "The results showed that the levels of caspase-11, GSDMD-NT, NLRP3, ASC, caspase-1, IL-1β, and IL-18 were increased in sepsis mice and that ST pre-treatment suppressed this effect." (PMID 34483936, 2021). "In septic patients, serum concentrations of IL-18 were negatively correlated with platelet counts suggesting a role of IL-18 in the development of severe thrombocytopenia during sepsis." (PMID 32998441, 2020).
Sepsis (continued). "They regulate at least two host responses during sepsis: maturation and secretion of the pro-inflammatory cytokines interleukin-1β (IL-1β) as well as IL-18 and induction of pyroptosis, a rapid lytic form of programmed cell death." (PMID 33613537, 2020). "RAPA terminated the excessive inflammatory response by maintaining the integrity of the membrane of sepsis cell model and reducing the release of IL-1β and IL-18 from these immune cells, which are the pivotal inflammation mediators in sepsis." (PMID 32851082, 2020). "In our previous report using sepsis model mice, we found an increased expression of IL-18 in CD4+ T cells of the spleen." (PMID 33344483, 2020). "IL-1β values decreased back to baseline levels on day 7, whereas increased levels of IL-18 were maintained in the serum during the first week of sepsis." (PMID 33613537, 2020). "The mRNA transcript levels of caspase-1, IL-1β, and IL18 were higher in patients with sepsis/ARDS when compared to patients with systemic inflammatory response syndrome and controls." (PMID 33149733, 2020). "Lower levels of IL-18 found in both sepsis groups can be explained by the overexpression of IL-10, because there is an inverse regulatory function between IL-10 and IL-18." (PMID 32295272, 2020). "Supporting this, blocking IL-17 down-regulated inflammation and conferred protection against sepsis and reduced mortality to both neonatal sepsis and endotoxemia by targeting IL-18." (PMID 32293300, 2020). "In conclusion, our study demonstrates that the measurement of FGF-2 and IL-18 levels in combination represents an effective biomarker for the differential diagnosis of AOSD from sepsis." (PMID 32381117, 2020). "Pyroptosis, an inflammatory form of programmed cell death, is the initiating event of sepsis and results in immune imbalance by releasing IL-1β and IL-18 in the early stages." (PMID 32851082, 2020). "In another study comparing patients with sepsis and AOSD, serum IL-18 levels were higher in patients with AOSD than in those with sepsis, which is consistent with our results." (PMID 32381117, 2020). "The best combination of cytokines to distinguish AOSD from sepsis was found to be IL-18 (> 543 pg/mL) and FGF-2 (> 36 pg/mL), with high accuracy observed (sensitivity 100%, specificity 72.2%, and accuracy 93.8%)." (PMID 32381117, 2020). "Circulating IL18 increases during sepsis and is strongly correlated with the severity of the disease." (PMID 30850654, 2019). "Elevated IL-18 levels have been demonstrated in patients with sepsis and ARDS compared to ICU controls." (PMID 31606045, 2019). "IL-18 is a pro-inflammatory cytokine, and the levels of it in CSF and plasma increase during bacterial meningitis and sepsis." (PMID 31803186, 2019). "Meanwhile, deficiency of SESN2 showed defective mitophagy, caspase-1 hyperactivation, and increased secretion of IL-1β and IL-18, which ultimately increased the mortality in murine sepsis." (PMID 31867002, 2019). "Overall from our study we show that targeting NGAL levels provides kidney injury during sepsis and is associated with the inflammatory stress that is enhanced in the presence of IL18, the critical mediator of sepsis." (PMID 30850654, 2019). "More specifically, IL18 increased dramatically in S24 and S48 groups, representing an early onset of the cytokine storm in the setting of sepsis." (PMID 30850654, 2019). "AOSD, RHS, and sepsis share pathophysiological aspects, including the prominent role of pro-inflammatory cytokines IL-1, IL-6, and IL-18." (PMID 29642928, 2018). "A corresponding deficit in NK-cell capacity to produce effector molecules following secondary infection and/or cytokine stimulation (IL-12,IL-18) further suggested a sepsis-induced NK-cell intrinsic impairment." (PMID 30379932, 2018). "Patients with poor disease outcomes from other critical illness, such as sepsis, also have elevated levels of IL-18." (PMID 27812211, 2016).